TYR (tyrosinase)
Diseases named in the same sentence as TYR in open-access papers (continued):
Sharing a sentence is not in itself a finding about the gene and the disease.
melasma (continued). "Microneedle RF treatment can be combined with the topical application of a tyrosinase inhibitor preparation; however, further research is needed before this procedure can be widely used in the treatment of melasma." (PMID 36231404, 2022). "Another substance that has recently been used to treat melasma is kojic acid, which acts as a tyrosinase inhibitor through copper chelation." (PMID 36231404, 2022). "At normal levels, this hormone can reduce the level of cyclical activity of adenosine monophosphate and tyrosinase in cells so that it plays a role in preventing melasma." (PMID 36942149, 2022). "Contributing to the browning of plant and fruit tissues and to the hyperpigmentation of the skin, leading to melasma or age spots, the research of possible tyrosinase inhibitors has attracted much interest in agri-food, cosmetic, and medicinal industries." (PMID 35682928, 2022). "Traditionally, melasma has been treated with topical agents, including hydroquinone (HQ) (tyrosinase inhibitor), tretinoin, glucocorticosteroids and various formulations." (PMID 36231404, 2022). "Tyrosinase is the key factor involved in inducing dermatological disorders, including age spots, freckles, and melasma." (PMID 34356311, 2021). "Tyrosinase is the key enzyme of melanin synthesis, and its overexpression can lead to pigmentation diseases such as freckles, chloasma and melanoma." (PMID 34206838, 2021). "In this specific case, an anti-tyrosinase activity is interesting when willing to treat issues such as melasma." (PMID 32967274, 2020). "Tyrosinase is a major rate-limiting enzyme of melanin biosynthesis, therefore tyrosinase inhibitors have been extensively explored for the treatment of dermatological issues, such as solar lentigines and melasma." (PMID 33050431, 2020). "In humans, the overexpression of tyrosinase leads to the overproduction of melanin in the skin, which can trigger hyperpigmentation effects such as freckles, melasma, age spots, and melanoma." (PMID 30320135, 2018). "Overproduction and stimulation of tyrosinase result in increased melanogenesis of which several skin disorders such as freckles, spots, and hyperpigmentation appear as complications." (PMID 28872626, 2017). "sFRP2 has been investigated to be overexpressed in melasma or UV-irradiated skin to stimulate melanogenesis through MITF or tyrosinase upregulation via β-catenin signaling." (PMID 27240341, 2016). "Findings in a study of the hyperpigmentation condition melasma, for example, supported the role of several ion transporters in the estrogen-induced expression of tyrosinase." (PMID 25789475, 2015). "AP736 was identified as an antimelanogenic drug that can be used for the prevention of melasma, freckles, and dark spots in skin by acting as a suppressor of melanin synthesis and tyrosinase expression." (PMID 25386046, 2014). "Thus, this study presents a novel investigation into the association of genetic polymorphisms in SLC45A2, TYR, HERC2, and SLC24A5 in African women with melasma, a population that has been under-represented in genetic research on pigmentation disorders." (PMID 39940926, 2025). "The excessive production of ROS can alter the structure of tyrosinase, leading to liver damage, which may disrupt melanin metabolism and contribute to melasma development." (PMID 40165336, 2025). "Additionally, ageing-related factors induces the overexpression of tyrosinase, which is a key enzyme in melanogenesis and pigmentary disorders such as melasma and senile lentigines." (PMID 40805647, 2025). "Findings from this study did not reveal any significant differences between the two study groups, suggesting that the rs1126809 of the TYR gene does not play a major role in melasma susceptibility." (PMID 39940926, 2025).
melasma (continued). "By examining polymorphisms in SLC45A2, TYR, HERC2, and SLC24A5, this pilot study highlights the potential genetic factors that may influence melasma susceptibility and severity in a population with distinct pigmentation characteristics." (PMID 39940926, 2025). "In fact, tyrosinase activity is very important: if uncontrolled it can result in increased melanin synthesis so that decreasing tyrosinase activity has been targeted for the improvement or prevention of conditions related to the hyperpigmentation of the skin, including melasma and age spots." (PMID 39735711, 2024). "Of them, topical hydroquinone inhibits tyrosinase and is the gold standard to treat melasma." (PMID 40255950, 2024). "Tyrosinase inhibitors are used to treat skin conditions such as hyperpigmentation and melasma." (PMID 37456762, 2023). "In the last decades, several extracts generated from plants were positively screened on TYR inhibition, which could be beneficial for repairing pigmentation problems such as freckles, melasma, age spots, and acne scars." (PMID 36770612, 2023). "Excessive melanin leads to melasma and age spots due to overexpression of tyrosinase." (PMID 35164177, 2022). "Since tyrosinase activity is critical during melanogenesis, by which pathological local hyperpigmentation such as melasma and lentigo occur, decreasing tyrosinase activity by using tyrosinase inhibitors has been widely tried as a treatment for hyperpigmentation disorder." (PMID 35956878, 2022). "Considering the important role that tyrosinase plays in the processing of fruit and vegetables and during the storage of processed foods, as well as in the hyperpigmentation of the skin with melasma and age spots, its inhibition is attractive in cosmetic, medicinal, and food industries." (PMID 35682928, 2022). "In addition, it has been believed that excessively active tyrosinase leads to the accumulation of melanin in the human skin, which results in various common skin diseases, such as freckles, melasma, and melanosis." (PMID 35783205, 2022). "Therefore, tyrosinase inhibitors are used in cosmetic and medicinal industries to prevent or treat overproduction of melanin such as melasma, solar lentigo and post inflammatory melanoderma." (PMID 31089372, 2019). "Tyrosinase inhibitors could be used in pharmaceutical and cosmetic industries for prevention and treatment of melanin overproduction-mediated diseases such as melasma, solar lentigines, and ephelides." (PMID 31089372, 2019). "Due to the over expression of tyrosinase, excessive melanin leads to melasma and age spots." (PMID 30364385, 2018). "Agents targeting these pathways, including tyrosinase inhibitors such as arbutin and kojic acid, and depigmenting agents like azelaic acid, have shown efficacy in managing melasma Personalizing treatment based on the patient’s genetic profile may enhance therapeutic outcomes." (PMID 39940926, 2025). "In contrast, the rs1126809 of the TYR gene did not exhibit significant associations with melasma." (PMID 39940926, 2025). "Additionally, EGF may inhibit prostaglandin-E2 (PGE2) expression and decrease tyrosinase enzyme activity; both are involved in the mechanism of melanin production and potentially contribute to the reduction in melasma or hyperpigmentation." (PMID 41149049, 2025). "Despite the antioxidant, anti‐tyrosinase, and illuminating properties of many medicinal plants and the several recommendations of traditional Persian medicine sources on the effect of these plants, few studies have investigated the effect of these plants on melasma‐induced skin spots." (PMID 39710951, 2025). "Therefore, tyrosinase (TYR) inhibitors could be the candidates for skin care products to repair pigmentation problems such as freckles, melasma, age spots, and acne scars." (PMID 36770612, 2023).
melasma (continued). "Here, we found that MITF overexpression can reverse the effects of pearl in melasma, suggesting the involvement of the MITF/TYR/DCT axis in the antimelasma mechanism of pearl." (PMID 40369904, 2025). "Conventional melasma or PIH treatments include topical whitening agents, such as tyrosinase inhibitors and hydroquinone, mequinol, and retinoids." (PMID 39519119, 2024). "Lastly, we assessed TYR, a marker of melanin synthesis and oxidative stress indicators SOD and MDA, validating the local autophagy markers such as LC3 and p62, without exploring newer or potentially more effective indicators for evaluating melasma." (PMID 40640993, 2026). "DNA sequencing revealed that TYR and DCT were genes related to melasma." (PMID 40369904, 2025). "However, despite these limitations, this pilot novel study demonstrates valuable insights into melasma development in women of African descent by exploring the genetic role of specific SNPs (SLC45A2, TYR, HERC2, and SLC24A5) in this under-represented population." (PMID 39940926, 2025). "Although several therapy options, including tyrosinase inhibitors, anti-inflammatory steroids, and topical retinoids, have been employed more often in studies, darker-complexioned individuals have not shown a noticeable improvement in melasma pigmentation." (PMID 41586372, 2025).
oculocutaneous albinism (64 papers, 2006 to 2026). Oculocutaneous albinism (OCA) describes a group of inherited disorders of melanin biosynthesis characterized by a generalized reduction in pigmentation of hair, skin and eyes and variable ocular findings including nystagmus, reduced visual acuity and photophobia. "Mutations in the tyrosinase or TRP-1 genes can result in oculocutaneous albinism, a group of autosomal recessive disorders characterized by reduced melanin production in the skin, hair, and eyes." (PMID 39897280, 2025). "Seven patients are compound heterozygotes for two pathogenic variants of the TYR gene and belong to the oculocutaneous albinism (OCA) type 1 (OCA1) subtype of the disease." (PMID 38279271, 2024). "Individuals with TYR-associated oculocutaneous albinism and those with RPE65-associated disease showed significantly increased odds for longer ALs (≥26 mm) and also for shorter ALs (≤22 mm)." (PMID 35704304, 2022). "An arginine-to-histidine substitution at the homologous site in TYR has been reported in humans and is associated with oculocutaneous albinism; thus, histidine at this site is likely disruptive to protein function." (PMID 36260636, 2022). "Only the well-described oculocutaneous albinism variants, TYR and OCA2, were significantly associated with skin colour (P = 2.19 x 10-4 & 2.31 x 10-3, respectively)." (PMID 33979322, 2021). "Tyr is the gene encoding the rate-limiting enzyme in melanin synthesis, the loss of which results in a complete failure to synthesize melanin and is manifested as oculocutaneous albinism in individuals with TYR mutations." (PMID 32151278, 2020). "On the other hand, mutations of the N-glycosylation sequons of TYR Asn337 and Asn371 have been found in patients with classic tyrosinase-dependent oculocutaneous albinism." (PMID 32019241, 2020). "In contrast, Asn371 mutations have been found in patients with classic tyrosinase-dependent oculocutaneous albinism." (PMID 32019241, 2020). "Whole exome or direct sequencing showed that two of the children had Hermansky-Pudlak syndrome (HPS) type-1 (HPS-1), one had HPS-3, one had HPS-4, and four had non-syndromic oculocutaneous albinism associated with TYR variants (OCA1)." (PMID 30791930, 2019). "For proper function and localization, TYR requires N-glycosylation at seven sites, and mutations at those sites are directly related to human oculocutaneous albinism (OCA), indicating the importance of this modification." (PMID 27092497, 2016). "Oculocutaneous albinism (OCA) occurs when mutations in the tyrosinase gene (TYR) lead to oculocutaneous albinism type 1 (OCA1) giving rise to nystagmus and hypoplasia as well as decreased visual acuity." (PMID 27698666, 2016). "Tyrosinase (TYR) catalyzes the rate-limiting, first step in melanin production and its gene (TYR) is mutated in many cases of oculocutaneous albinism (OCA1), an autosomal recessive cause of childhood blindness." (PMID 24392141, 2014). "We next investigated whether inlaid Nme2ABE can be used to mimic the disease-relevant point mutations of the TYR mutation (p.D42G), which is the major causal genetic mutation responsible for human ocular albinism (OA) and oculocutaneous albinism (OCA) in mice." (PMID 37946200, 2023). "Mutations in the gene encoding tyrosinase (Tyr) cause oculocutaneous albinism (OCA1) in humans." (PMID 27224051, 2016). "Oculocutaneous albinism (OCA) is a heterogeneous group of autosomal recessive disorders resulting from mutations of the tyrosinase (TYR) gene and presents with either complete or partial absence of pigment in the skin, hair and eyes due to a defect in an enzyme involved in the production of melanin." (PMID 25216246, 2014). "Mutations in the TYR gene may cause oculocutaneous albinism." (PMID 38632618, 2024). "Oculocutaneous albinism (OCA) is the result of a recessive mutation of the gene encoding the tyrosinase enzyme and is characterised by different levels of skin, hair, and eye pigmentation." (PMID 26018869, 2015).
oculocutaneous albinism (continued). "Patients with Hermansky-Pudlak syndrome (HPS) typically present with a triad comprising tyrosinase-positive oculocutaneous albinism, a tendency to bleed easily, and ceroid accumulation in multiple tissues." (PMID 40486412, 2025). "Two women were randomly selected for simulated matching testing: a healthy woman (female 1) without pathogenic variants and another (female 2) who was an autosomal recessive carrier of oculocutaneous albinism (TYR (NM000372.5) c.896G > A p.Arg299His)." (PMID 39757988, 2025). "Mutations to its gene (TYR) are linked to oculocutaneous albinism (OCA), specifically the OCA1 subtype." (PMID 40568124, 2025). "Inactivating mutations in these genes have been reported to cause oculocutaneous albinism (OCA), that is, TYR mutations cause OCA1, SLC45A2 mutations cause OCA4, and SLC24A5 mutations cause OCA6." (PMID 40741336, 2025). "Patients with the Hermansky-Pudlak syndrome (HPS) present with a triad, including tyrosinase-positive oculocutaneous albinism, bleeding tendency, and deposition of ceroid in various tissues." (PMID 40486412, 2025). "Oculocutaneous albinism in humans (human synonym OCA1) was obtained via the knockout of the Xenopus tyrosinase gene, producing similar phenotypic outcomes, but it requires the co-targeting of two gene homeologs because of the allotetraploidy of X. laevis." (PMID 37372174, 2023). "The patient was referred for genetic testing and the results confirmed the diagnosis of tyrosinase-positive oculocutaneous albinism (OCA2)." (PMID 37790023, 2023). "rs1042602 (c.575C>A), first found in patients with Oculocutaneous Albinism, is a missense variant within the TYR locus, which codes for tyrosinase, a key enzyme that controls the first steps in melanogenesis." (PMID 36556369, 2022). "These include rs1800407 and rs1042602, at loci previously associated with oculocutaneous albinism (in OCA2 and TYR respectively)." (PMID 33979322, 2021). "OCA1 and OCA2 are caused by mutations of the TYR and OCA2 genes, respectively, which are responsible for most oculocutaneous albinism." (PMID 31196117, 2019). "Hermansky-Pudlak syndrome (HPS) is a heterogeneous group of genetic disorders typically manifesting with tyrosinase-positive oculocutaneous albinism, bleeding diathesis, and pulmonary fibrosis, in some subtypes." (PMID 28296950, 2017). "Mutations in TYR, OCA2, TYRP1, and SLC45A2 are mainly responsible for causing oculocutaneous albinism." (PMID 25093188, 2014). "Tyrosinase folding is further decreased upon gene mutations, with some mutants reported to be ERAD substrates in oculocutaneous albinism." (PMID 22905195, 2012). "Mutations in the TYR gene cause the most severe form of oculocutaneous albinism OCA1 (TYR, MIM 606933, OCA1, MIM 203100)." (PMID 21559390, 2011). "According to her history, HPS was diagnosed elsewhere in 2002 [tyrosinase-positive oculocutaneous albinism (Ty-pos OCA) and normal platelet count with small quantity of dense bodies (DB), without genetic linkage analysis]." (PMID 18067668, 2007). "TYR mutants may also result in oculocutaneous albinism, pigment dispersion syndrome, or pigmentary glaucoma in the eye." (PMID 38632618, 2024). "Of 19 diseases, 10 had >10 participants: ABCA4 retinopathy; CNGB3- and CNGA3-associated achromatopsia; RPGR-associated disease; RPE65-associated disease; blue cone monochromacy (BCM); Bornholm eye disease (BED); TYR- and OCA2-associated oculocutaneous albinism; and GPR143-associated ocular albinism." (PMID 35704304, 2022). "OCA2 was first identified in 1993, in a patient with tyrosinase-positive oculocutaneous albinism." (PMID 34707637, 2021). "Oculocutaneous albinism (OCA) is an inherited condition caused by a deficiency or absence of tyrosinase activity, a key enzyme in melanin biosynthesis by melanocytes in the skin, hair follicles, and eyes." (PMID 34976411, 2021).
oculocutaneous albinism (continued). "On the other hand, we highlight many pathologies which are at relatively high risk in Russia, including Wilson's disease, factor VII deficiency, Stargardt disease, tyrosinase‐negative oculocutaneous albinism, and several other diseases." (PMID 31482689, 2019). "Several types of inherited hypopigmentary diseases, such as oculocutaneous albinism and Hermansky-Pudlak syndrome, involve the aberrant processing and/or trafficking of tyrosinase and its subsequent degradation which can occur due to the quality-control machinery." (PMID 20057953, 2009). "Hermansky-Pudlak syndrome (HPS) is a complex syndrome with a triad of manifestations of tyrosinase-positive oculocutaneous albinism (Ty-pos OCA), bleeding diathesis resulting from platelet dysfunction, and systemic complications associated with accumulation of ceroid lipofusion." (PMID 18067668, 2007). "In humans, mutations in TYR result in oculocutaneous albinism (OCA) type 13, whereas mutations in TYRP1 or TYRP2 give rise to OCA type 34 or OCA type 85, respectively." (PMID 37072620, 2023). "Impaired TYR maturation is common to several forms of the group of genetic disorders known as oculocutaneous albinism (OCA) in humans." (PMID 33995009, 2021). "In a human case, a single base insertion located in the transmembrane domain of the tyrosinase gene eliminated a portion of the transmembrane region and the carboxy terminus, and resulted in an inactive enzyme causing tyrosinase-negative oculocutaneous albinism." (PMID 16457736, 2006). "The absence of enzymatically active tyrosinase is the main cause of oculocutaneous albinism IA (OCA IA)." (PMID 21625599, 2011). "Genetic defects in expression of some melanogenic enzymes (TYR, TYRP1) or other melanin synthesis regulators (P protein, SLC45A2,) result in oculocutaneous albinism (OCA1-OCA4) and visual function impairment, demonstrating the importance of melanin for proper ocular function." (PMID 35682684, 2022).